SNORD116-18 (small nucleolar RNA, C/D box 116-18)
Synonyms: HBII-85-18
Gene: Small nucleolar RNA gene on chromosome 15 (25,085,385 to 25,085,476, forward strand). Ensembl gene ENSG00000206688.
Gene Ontology:
Biological process: RNA processing
Cellular component: nucleolus
Homologues: Orthologues: macaque SNORD116 (99% identical), guinea pig SNORD116 (89% identical), guinea pig SNORD116 (85% identical). Paralogues in human: SNORD116-17 (99% identical), SNORD116-19 (99% identical), SNORD116-14 (98% identical), SNORD116-15 (98% identical), SNORD116-20 (98% identical), SNORD116-21 (98% identical), SNORD116-22 (98% identical), SNORD116-16 (96% identical), SNORD116-12 (92% identical), SNORD116-23 (92% identical), SNORD116-24 (92% identical), SNORD116-2 (88% identical), and 20 more.